FSCN3 (fascin actin-bundling protein 3)
Description:
Acts as an actin bundling protein.
Tractability: No criterion of Open Targets' tractability assessment is met for any kind of drug.
Gene: Protein-coding gene on chromosome 7 (127,591,409 to 127,602,144, forward strand). Ensembl gene ENSG00000106328.
Subcellular location: Cytoplasm, cytoskeleton
Gene Ontology:
Molecular function: actin filament binding; protein-macromolecule adaptor activity
Biological process: actin filament bundle assembly; cell migration; establishment or maintenance of cell polarity; actin filament organization
Cellular component: actin cytoskeleton; cell projection membrane; cytoplasm; cytoskeleton; filopodium; growth cone; lamellipodium; microvillus; ruffle
Genetic constraint (gnomAD): Loss-of-function variants: 36 observed, 42.54 expected, observed/expected ratio (o/e) 0.85, 90% interval 0.65 to 1.12. The upper end of that interval is the gene's LOEUF score, 1.12, which puts it in group 4 of 6, group 1 being the genes least tolerant of losing a copy. Missense variants: 494 observed, 562.69 expected, observed/expected ratio (o/e) 0.88, 90% interval 0.81 to 0.95. Synonymous variants: 202 observed, 220.38 expected, observed/expected ratio (o/e) 0.92, 90% interval 0.82 to 1.03.
Homologues: Orthologues: chimpanzee FSCN3 (99% identical), macaque FSCN3 (96% identical), rabbit FSCN3 (87% identical), mouse Fscn3 (85% identical), pig FSCN3 (84% identical), dog FSCN3 (82% identical), guinea pig FSCN3 (81% identical), rat Fscn3 (73% identical), Drosophila melanogaster sn (23% identical). Paralogues in human: FSCN1 (27% identical), FSCN2 (27% identical).
Diseases named in the same sentence as FSCN3 in open-access papers:
FSCN3 is named in the same sentence as 4 diseases in open-access papers, as found by Europe PMC text mining. Sharing a sentence is not in itself a finding about the gene and the disease. The quoted sentences say what the papers report.
Azoospermia (1 paper, 2023). Absence of any measurable level of sperm,whereby spermatozoa cannot be observed even after centrifugation of the semen pellet. "The regulatory network of TF-miRNA-mRNA and lncRNA-miRNA-mRNA was predicted and revealed that has-miR-3127-5p and has-miR-3184-5p might be the regulator of PRM2、FSCN3 and TEKT2 and play a critical role in azoospermia and TGCT." (PMID 37891374, 2023).
male infertility (1 paper, 2023). The inability of the male to effect fertilization of an ovum after a specified period of unprotected intercourse. "Among them, miRNAs (has-miR-3127-5p and has-miR-3184-5p), lncRNAs (AL356488.2 and AL645608.3) and TFs (NANOG and HEY1) as the key regulatory factors of PRM2, FSCN3 and TEKT2, were predicted significantly associated with male infertility." (PMID 37891374, 2023).
testicular germ cell tumor (1 paper, 2023). A germ cell tumor arising from the testis. "Three of them (PRM2, FSCN3 and TEKT2) were significantly down-regulated in the testicular germ cell tumors and their methylation levels were associated with the pathogenesis." (PMID 37891374, 2023).
FSCN3 also shares sentences with these, for which no sentence is quoted: asthenozoospermia (1 paper).